TTTY19 (testis expressed transcript, Y-linked 19)
Synonyms: NCRNA00144
Gene: Long non-coding RNA gene on chromosome Y (8,704,472 to 8,705,283, forward strand). Ensembl gene ENSG00000232419.
Diseases named in the same sentence as TTTY19 in open-access papers:
TTTY19 is named in the same sentence as 1 disease in open-access papers, as found by Europe PMC text mining. Sharing a sentence is not in itself a finding about the gene and the disease.
TTTY19 shares sentences with these, for which no sentence is quoted: non-small cell lung carcinoma (1 paper).